CD44 (CD44 molecule (IN blood group))
Diseases named in the same sentence as CD44 in open-access papers (continued):
Sharing a sentence is not in itself a finding about the gene and the disease.
tumor (continued). "These tumor enriched CD44 variants represent ideal cell-surface markers for aptamer nanoprobe development that can specifically target HCC cells." (PMID 34976591, 2022). "CD44 has additional splice variants that are significantly involved in tumor formation and progression." (PMID 36313570, 2022). "Categorical univariate Cox regression showed that ZEB1+snail+ tumour cells and snail+CD44+ tumour cells were associated with longer OS and 5-year survival." (PMID 36358805, 2022). "CD44, a putative tumor stem cell marker, was significantly associated with C7, CXCL6, CLEC1B, and GPR182 in Hep3B cells and with C7, CXCL6, CLEC1B, and IL1RL1 in Huh7 cells." (PMID 36307751, 2022). "High expression of CD44 has been associated with self-renewal, tumor initiation, metastasis, and resistance to apoptosis, chemotherapy, and radiotherapy." (PMID 35326517, 2022). "To note, in vitro studies using RCC cell lines observed that CD44 was upregulated in the presence of tumour-associated macrophages (TAMs)." (PMID 36358805, 2022). "The expression of MUC1, CD44, and HA has been notably implicated in tumor cell migration and metastasis via several signaling pathways." (PMID 36359337, 2022). "Different CD44 isoforms (CD44v) functionally distinct from the standard isoform (CD44s) can be formed through alternative splicing, associated with tumor growth and metastasis." (PMID 35456655, 2022). "CD44 is a well-characterized cell surface glycoprotein receptor associated with a subpopulation of resilient tumor cells with enhanced carcinogenic properties specially involved with increased cell migration." (PMID 33976322, 2021). "CD44 intracellular signaling in response to extracellular signals is reported as a mediator of the link between tumor-associated macrophages in the tumor microenvironment and CSCs." (PMID 34359786, 2021). "Analysis of division status and phenotype revealed that the combination of tumor inoculation and CTXpre/CD4post caused most Thy1.1+ Pmel-1 cells to rapidly divide and differentiate into the CD44+ CD62L− effector memory phenotype." (PMID 34493727, 2021). "Mounting evidence showed that a cluster of differentiation 44 (CD44) molecule is an important tumor protein associated with metastasis." (PMID 34599251, 2021). "Group 2 was characterised by tumour samples exhibiting low expression of BMI-1/CD44 and high expression of ALDH1/Nanog/SOX2 associated with a lower grading." (PMID 33009929, 2021). "With tumor sphere-formation in CD133+/ CD44+ MiaPaCa2 cells, loss of miR-34 and increase of Notch/Bcl-2 has been reported." (PMID 34094034, 2021). "Our results also demonstrated that tumor growth caused by CD44+CD133+ tumor-initiating Caco-2 cells separated from the primary tumor was faster than that in primary xenografts." (PMID 33994850, 2021). "In HNC, CD44 + expression has been associated with tumor-initiating cells or cancer stem cells due to their ability to persist and self-renew following therapy." (PMID 33976322, 2021). "Pathogenetically, in several tumour models, up-regulation of CD44 and/or its variants has been linked to inflammation, the relevant mediators and the changes induced by chronic inflammation." (PMID 34884696, 2021). "Numerous investigations support the role of cancer stem cells (CSCs) and their associated markers in tumour malignancies, for example, the cluster of differentiation 44 or CD44." (PMID 34944493, 2021). "Recently, CD44, a surface glycoprotein, was highly implicated in the regulation of tumor progression, invasion, and metastasis." (PMID 34205649, 2021). "CD44 is one such marker of cancer stem cells and CD44-positive tumor cells were shown to be associated with tumor initiation, metastasis and prognosis." (PMID 34064540, 2021). "The expression of CD44 variant isoforms, the cleavage of CD44, and the production of hyaluronan increases in stem-like tumor cells grown in spheres." (PMID 33804427, 2021).
tumor (continued). "Here, we showed for the first time that the anti-tumor capability of BM CM was linked to the regulatory network of Hsp90ab1, Eno1, Ubc, CD44, and LAP-TGFβ." (PMID 34830748, 2021). "Variant 6 of CD44 (CD44v6) participates in tumor development and progression in many ways that are restricted to stem cell subpopulations." (PMID 33451103, 2021). "The interaction between CD44 and its primary ligand, i.e., hyaluronic acid, has been implicated in tumor migration, proliferation, and tumor clonogenicity." (PMID 34833970, 2021). "The V6 exon-containing isoforms of CD44 mRNA (CD44 V6) have been implicated in tumorigenesis by promoting tumor cell invasion and metastasis 74-76." (PMID 33994855, 2021). "The higher frequency of CD44-/CD24- tumor cells is associated with delayed distant metastasis and worse DFS in the testing group of patients." (PMID 34318746, 2021). "After this screening, only CD44 expression showed significant clinical impact at the translational level being associated with tumor recurrence." (PMID 33976322, 2021). "Similar results were achieved in the training set of patients following chemotherapy and the patients with a higher frequency of CD44-/CD24- cells had a higher risk to develop distant metastasis beginning at 4 years post tumor resection." (PMID 34318746, 2021). "At single-cell resolution, only malignant tumor cells, tumor-associated macrophages (TAMs), and T cells express CD44 in GBM." (PMID 35187044, 2021). "Organotropism of TEVs, such as CD44+TEVs, exemplifies the potential steps underlying the mechanisms involved in cancer metastasis; a critical step in determining the outcome of tumor treatment." (PMID 33540535, 2021). "In contrast, some studies found low expression of CD44 or its variants was correlated with increased tumor recurrence, short disease-free survival and tumor progression." (PMID 34214117, 2021). "It is reported that CD44 is associated with increased potential for tumor initiation and progression." (PMID 33588867, 2021). "CD44 is another cell surface marker frequently used in GBM studies as well as other tumour types and is associated with tumour invasion and aggressive growth of GBM tumours." (PMID 34066147, 2021). "CD44 variant, a cancer stem-like cell marker, stabilizes the xCT antiporter at the cellular membrane, and tumor cells positive for xCT and/or ASCT2 are susceptible to sulfasalazine, a system Xc(-) inhibitor." (PMID 33401672, 2021). "In the same work, it was shown that HA upregulated genes associated with matrix remodeling and tumor growth generating resistance to the EGFR inhibitor erlotinib depending on CD44/PI3K axis." (PMID 33744285, 2021). "Malignant cells expressing CD44 are associated with tumor initiation and tumorsphere formation capacity that leads to cancer progression and poor patient outcome." (PMID 33594192, 2021). "It has been well reported that VM formation is associated with phenotype switching or “cell stemness” (i.e., tumour cell plasticity), which is mediated by certain events such as upregulation of CD44 and loss of epithelial cell markers including E-cadherin." (PMID 34638234, 2021). "The epithelial-specific antigen (ESA)(+)/CD44 molecule and Indian blood group (CD44)(+) CRCSCs are associated with tumor recurrence after chemotherapy." (PMID 33917482, 2021). "CCL2+ TAMs are related to the immune response and exhibit a high capacity for apoptosis, while CD44+ TAMs are associated with tumor angiogenesis." (PMID 34824203, 2021). "They demonstrated that the loss of CD44 attenuated tumour cell adhesion to endothelial cells and reduced cell invasion, but did not affect proliferation in vitro." (PMID 35006432, 2021). "Among all CD44 isoforms, CD44v6 harboring a mutation in exon 11 plays an important role in enhancing the adhesive ability of tumor cells." (PMID 34400947, 2021). "Increased level of CD44 protein in serum is observed in several cancers and is associated with tumor burden and metastasis." (PMID 34599251, 2021).
tumor (continued). "Urinary CD44 was measured using RT-qPCR and was positively associated with tumor aggressiveness in UC." (PMID 33445605, 2021). "CD44 is induced in aberrant crypt foci in both humans and tumor-susceptible ApcMin/+ mice, and its deletion in ApcMin/+ mice inhibits the formation of aberrant crypt foci and intestinal tumorigenesis." (PMID 34788095, 2021). "In this study, we investigated the expression and function of CD44 variants and xCT in canine tumours." (PMID 33210459, 2021). "IHC staining confirmed protein expression of all five stemness-associated markers and the CSC marker CD44, in nuclear and cytoplasmic locations within the tumor and stromal cells, depending on the marker and patient sample." (PMID 34685477, 2021). "CD44 marker was positively associated with S phase (rho = 0.396, p = 0.01), tumor stage, and tumor grade (rho = 0.65, p < 0.0001) but negatively correlated with early apoptosis (rho = - 0.525, p = 0.001)." (PMID 34837915, 2021). "CD44 expression was associated with high-risk of tumor recurrence and metastasis (P = 0.01) in HPV-cases." (PMID 33976322, 2021). "In contrast, CD44+ TAMs expressed high levels of angiogenesis-associated genes and tended to interact with endothelial cells, pericytes and fibroblasts to facilitate tumor angiogenesis." (PMID 34824203, 2021). "Elevated expression of CD44 in serum has been shown to associate with the presence of distant metastases and tumor reoccurrence." (PMID 34599251, 2021). "CD44 plays a multi-functional role, such as related to cancer stem cells and tumor-associated macrophages, leading to drug resistance of recurrent chemotherapy drugs in OC." (PMID 34526089, 2021). "We previously showed that the CD44 variant form is required for gastric tumorigenesis through the protection of tumor cells from ROS-induced damage." (PMID 33795838, 2021). "CD44v6, another splice variant of CD44 containing exon v6, has a higher affinity for hyaluronic acid than CD44s, further implicating this CD44 variant in tumor pathology." (PMID 34290978, 2021). "CD44, a tumor-initiating marker, and total protein have been associated with HNSCC in case-control studies." (PMID 33530399, 2021). "For many years, activation of CD44 pathways has been implicated in GBM as responsible for various tumor supportive signaling pathways, such as cell motility, cell proliferation, invasion, angiogenesis and drug resistance." (PMID 33911148, 2021). "High expression of CD44 is associated with tumour aggressiveness and poor outcome and CD44 inhibition can impair tumour growth." (PMID 34332294, 2021). "CD44 confers several variant isoforms, some of which are found to be upregulated in tumor progression." (PMID 33050539, 2020). "CD44 undergoes extensive alternative splicing during tumor progression, generating two families of isoforms: the CD44 variant (CD44v) and CD44 standard isoform (CD44s)." (PMID 33024087, 2020). "We further report that although loss of carcinoma cell CD44 has little impact on overall animal survival by tumor burden, there is a dramatic delay in tumor growth relative to mock controls." (PMID 32455980, 2020). "The expression of CD44 and its variant isoforms relates to tumor progression and recurrence in some cancers." (PMID 32039729, 2020). "CD44 variant isoforms, in particular those containing CD44 variant domain 6 (CD44v6), have been implicated in tumorigenesis, tumor cell invasion and metastasis." (PMID 32117253, 2020). "The v6 splice variant of CD44 (CD44v6) is involved in tumorigenesis, tumor cell invasion, and metastasis." (PMID 32560337, 2020). "Tumor cell behaviors, including proliferation, survival, migration/invasion, and chemoresistance, are closely associated with upregulation of CD44." (PMID 32466488, 2020). "Since SFN blocked the tumor growth and proliferation, it is likely that these CD44 variants contributed to this process." (PMID 33218199, 2020).
tumor (continued). "CD44 is an important protein that has been implicated in tumor progression and resistance to therapy." (PMID 31973075, 2020). "There is considerable evidence suggesting that a high expression of CD44 is associated with tumor progression and recurrence, which is similar to the other two variant isoforms that have also been reported to be involved in cancer progression and recurrence." (PMID 32039729, 2020). "CD44 variant isoforms are often upregulated in cancer and associated with increased aggressive tumor phenotypes." (PMID 31973075, 2020). "The homogeneous versus heterogeneous CD44 expression in ED03 compared with EDW01 associates with the interruption of growing tumour by murine stroma, as illustrated by Masson’s Trichrome staining, where connective tissue stains blue." (PMID 33276802, 2020). "Among ten CD44 variants, CD44v9 has been closely associated with cellular processes and tumorigenicity comprising cell proliferation, metastasis, and tumor invasiveness through epithelial-mesenchymal transition (EMT)." (PMID 32582701, 2020). "All tumor spheres expressed the variant 6 isoform of adhesive receptor CD44 (CD44v6), a cell surface protein expressed in CSCs of several cancer types but not in somatic cells." (PMID 32737364, 2020). "High expression of CD44 is associated with tumor aggressiveness, drug resistance, and poor treatment outcome." (PMID 32927646, 2020). "The variant isoforms of CD44 (CD44v) generated by alternative splicing have been reported to reveal higher aggressive potential in tumor as compared to the standard isoform (CD44s)." (PMID 32582701, 2020). "Altered E-and N-cadherin levels and the following β-catenin activation promote the expression of many tumor-associated proteins, including cyclin D1, CD44, or c-MYC." (PMID 32340207, 2020). "Hyaluronic acid can bind with several cell surface receptors such as CD44, which is always found in tumor ECM and is associated with tumor progress." (PMID 32784890, 2020). "Intermittent exposure to radiation (fractionated doses of radiation) cause a Notch-1 mediated enrichment of the tumor-initiating CD44+/CD24neg/low side population in the MCF7 cell line." (PMID 32883003, 2020). "We demonstrated the effectiveness of the dual mTORC1-2 inhibitor Rapalink-1 in reducing PCa tumor growth, an effect that was associated with the depletion of CD44+ cells in a PDX model of advanced, bone metastatic PCa." (PMID 32656088, 2020). "Patients with HCC overexpress CD44, and this expression is associated with tumor growth, metastasis, and poor prognosis." (PMID 32184825, 2020). "IL-6 produced by tumor-associated macrophages (TAMs) can activate the STAT3 signaling pathway to promote CD44+ LCSCs." (PMID 33117795, 2020). "The roles several famous splicing variants play in tumour progression, such as CD44, have been well studied." (PMID 32596958, 2020). "The CD44v8-10 has been claimed to be the predominant CD44 variant found in gastric CSCs from patient tumor samples, and its expression was shown to promote resistance against reactive oxygen species (ROS) and contributed to cell proliferation." (PMID 31973075, 2020). "The isoform containing the variant domain 6 of CD44 gene (CD44v6) has been implicated in tumorigenesis, tumor cell invasion and metastasis and represents an attractive target for CAR T cell therapies." (PMID 32117253, 2020). "Cross-communication between CD44 and Akt has recently been observed in drug resistant tumor cells, whereby enhanced CD44 expression is associated with Akt activation, driving tumor invasion forward." (PMID 32759798, 2020). "We next tested if the improved immune environment caused by CD44-targeted NIR-PIT can sensitize MOC2-luc tumor to the ICI." (PMID 33322807, 2020). "It has been previously reported in different tumors that the expression of CD44 increases in tumor tissue and is associated with tumor progression." (PMID 32610620, 2020).
tumor (continued). "In turn, evidence suggest that LMWHA associates with CD44, triggering the activation of specific signalling pathways that enhance invasion and metastatic ability of tumor cells." (PMID 31361756, 2019). "Despite its elevated expression on progenitor-like tumor-initiating cells, deletion of CD44 in a mouse model of luminal breast cancer susceptibility increases rather than decreases metastases." (PMID 31134064, 2019). "CD44 encodes for a cell-surface glycoprotein and can act both as a growth- and invasiveness-promoting molecule, and as a tumour-suppressing cofactor via its different splice variants." (PMID 30857150, 2019). "After 14 days of treatment, CUR-loaded CSO-SA micelles also caused a reduction in tumor size and the subpopulation of CD44+/CD24+ cell in nude mice tumor tissue." (PMID 30890933, 2019). "Expression of CD44-v10 in metastatic lesions was associated with decreased survival, while expression of CD44s in the primary tumor and the tumor-stroma interface was associated with improved survival." (PMID 31497537, 2019). "Both the standard and the variants can all be recognized by an antibody directed against the standard region but importantly, the expression of CD44 variants has only been found in cancer cells and has been reported as produced during tumor progression." (PMID 31139149, 2019). "Significant decrease (T2) or near loss (T1) of CD44 signal in the tumor stroma was confirmed by IHC with antibodies specific for mouse CD44 protein." (PMID 31762938, 2019). "Alternative splicing of the gene encoding for CD44 produces CD44 standard (CD44s) and CD44 variant (CD44v) forms numbered from v1 to v10, some of which have been found to increase in tumor progression and metastasis." (PMID 30754655, 2019). "CD44 variant isoforms are highly expressed in carcinomas of epithelial origin and relate to tumour progression and metastatic potential of some cancers." (PMID 31345216, 2019). "In HNSCC tumours, p63 expression is positively correlated with that of HAS3 and CD44, and the expression of three tumour‐related CD44 variants is associated with HNSCC progression in clinical samples." (PMID 30845357, 2019). "The expression of CD44 variants on the surface of tumor cells was related to different PCa characteristics and seems to be associated with invasive and metastatic behavior." (PMID 30754655, 2019). "CD44 is a well-characterized marker associated with treatment resistance and aggressive tumor growth." (PMID 31315262, 2019). "CXCR4 was expressed in a minority of tumour cells but, interestingly, >80% of these co-expressed the cell surface markers CD44 and CD166, which are associated with NSCLC tumour-initiating activity." (PMID 30792442, 2019). "CD44 expression is associated with stem cell-ness in tumor cells, but it is also expressed under hypoxic conditions or in epithelial cells and is a marker for effector memory T cells." (PMID 31998639, 2019). "The minimum biomarkers for BCSCs are the cell-surface markers CD44+/CD24- and CD44 upregulation is linked to tumor formation." (PMID 31480284, 2019). "CD44 also plays important roles in the differentiation, invasion and metastasis of tumor cells, is associated with poor clinical outcomes in cancer patients." (PMID 31682231, 2019). "ALDH concentrations have been directly associated with increased tumor size and symptoms of cancer in cell lines of HNSCCs cancer Apart from CD44 a broad of range of markers have been investigated in CSCs and specifically HNSCCs." (PMID 31030466, 2019). "Subsequent studies demonstrated that CD44 in primary tumors was associated with a more advanced stage, larger tumor size, and more prevalent lymph node metastases." (PMID 30056567, 2019).